ZHX3 (zinc fingers and homeoboxes 3)
Description:
Acts as a transcriptional repressor. Involved in the early stages of mesenchymal stem cell (MSC) osteogenic differentiation. Is a regulator of podocyte gene expression during primary glomerula disease. Binds to promoter DNA.
Synonyms: KIAA0395; TIX1
Tractability: Small molecule: it has a binding pocket of medium quality. PROTAC: ubiquitination databases record sites on it; its protein half-life has been measured.
Gene: Protein-coding gene on chromosome 20 (41,178,448 to 41,317,731, reverse strand). Ensembl gene ENSG00000174306.
Subcellular location: Nucleus
Subcellular location (Human Protein Atlas): Nucleoplasm
Gene Ontology:
Molecular function: DNA-binding transcription factor activity; protein binding; protein heterodimerization activity; protein homodimerization activity; DNA-binding transcription factor activity, RNA polymerase II-specific; DNA binding
Biological process: negative regulation of DNA-templated transcription; positive regulation of osteoblast differentiation; regulation of transcription by RNA polymerase II
Cellular component: nucleoplasm; nucleus; chromatin
Genetic constraint (gnomAD): Loss-of-function variants: 20 observed, 67.56 expected, observed/expected ratio (o/e) 0.3, 90% interval 0.21 to 0.43. The upper end of that interval is the gene's LOEUF score, 0.43, which puts it in group 1 of 6, group 1 being the genes least tolerant of losing a copy. Missense variants: 1,041 observed, 1,258.7 expected, observed/expected ratio (o/e) 0.83, 90% interval 0.79 to 0.87. Synonymous variants: 423 observed, 485.59 expected, observed/expected ratio (o/e) 0.87, 90% interval 0.8 to 0.94.
Homologues: Orthologues: chimpanzee ZHX3 (99% identical), macaque ZHX3 (98% identical), rabbit ZHX3 (89% identical), guinea pig ZHX3 (87% identical), pig ZHX3 (87% identical), mouse Zhx3 (85% identical), rat Zhx3 (85% identical), dog ZHX3 (84% identical), tropical clawed frog zhx3 (48% identical), zebrafish zhx3b (41% identical), zebrafish zhx3a (22% identical). Paralogues in human: ZHX1 (31% identical), ZHX2 (28% identical), HOMEZ (13% identical).
Diseases named in the same sentence as ZHX3 in open-access papers:
ZHX3 is named in the same sentence as 20 diseases in open-access papers, as found by Europe PMC text mining. Sharing a sentence is not in itself a finding about the gene and the disease. The quoted sentences say what the papers report.
breast carcinoma (4 papers, 2021 to 2025). "The increased ZHX3 expression was associated with good outcomes in breast cancer patients, indicating that ZHX3 might act as a prognostic biomarker for breast cancer patients." (PMID 36232466, 2022). "Zinc finger and homeobox 3 (ZHX3), a ubiquitous transcriptional repressor, has been reported to participate in various cancers, including bladder cancer, breast cancer, gastric cancer and renal cancer." (PMID 35125116, 2022). "Consistent with our recent reports in liver cancer and breast cancer, increased ZHX3 expression has been found to be correlated with a favorable OS in patients with lung cancer and may be of value to predict the outcomes of patients with early-stage disease." (PMID 41480542, 2025). "In addition, the mRNA expression of ZHX2 and ZHX3 were also positively associated with the estrogen receptor and progesterone receptor, but ZHX2 mRNA expression was inversely correlated with HER2 in breast cancers." (PMID 36232466, 2022). "Both ZHX2 and ZHX3 expressions were remarkably reduced in TNBC tissues, and a high mRNA expression of ZHX2 and ZHX3 were closely associated with a better prognosis of breast cancer patients, especially in luminal A subtype breast cancer." (PMID 36232466, 2022). "Interestingly, ZHX3 has also shown to act as a tumor suppressor in renal cell carcinoma, breast cancer, and liver cancer." (PMID 33962398, 2021). "In breast cancer, a negative ZHX3 expression was correlated with lymph node metastasis, poor differentiation, advanced tumor stage, and positive estrogen receptor expression." (PMID 36232466, 2022). "The biological functions of ZHX3 in cancer have not been well characterized, but limited studies have shown that ZHX3 is a tumor suppressor in HCC, non-small cell lung cancer, breast cancer, and renal cancer." (PMID 36232466, 2022).
gastric cancer (3 papers, 2021 to 2025). A primary or metastatic malignant neoplasm involving the stomach. "It has also been reported that an increased ZHX3 expression is associated with the progression of bladder carcinoma and gastric cancer, indicating that ZHX3 is involved in oncogenic programs." (PMID 36232466, 2022). "IHC staining confirmed that gastric cancer patients with a high ZHX3 expression have a worse prognosis." (PMID 36232466, 2022). "The Zinc-fingers and homeoboxes 3 (ZHX3) and ZNF93 had been reported to be significantly increased and were associated with poor prognosis in gastric cancer 22 and ovarian cancer 23, respectively." (PMID 33976729, 2021). "ZHX3 expression can also be used as a prognostic indicator for gastric cancer." (PMID 36232466, 2022). "Taken together, these data suggest that ZHX2 and ZHX3 act as oncogenes in gastric cancer." (PMID 36232466, 2022). "By contrast, gastric cancer patients with a decreased ZHX2 and ZHX3 mRNA expression showed better outcomes." (PMID 36232466, 2022). "Reduced ZHX2 and ZHX3 expression was remarkably correlated with a longer survival time in the subgroups of GC patients without lymph node metastases or distant metastasis, suggesting that the low expression of ZHX2 and ZHX3 predicts a better prognosis for early-stage gastric cancer patients." (PMID 36232466, 2022).
bladder cancer (2 papers, 2022 to 2023). "Bladder cancer patients with high ZHX3 expression had poorer disease-free survival and shorter overall survival rates." (PMID 37627900, 2023). "ZHX3 was found to be highly expressed in bladder cancer tissues and cell lines, thus indicating that ZHX3 is upregulated in bladder cancer." (PMID 37627900, 2023). "The overexpression of ZHX3 in bladder cancer T24 cells significantly increased cell migration and invasion." (PMID 37627900, 2023). "The knockdown of RGS2 markedly restored the abilities of migration and invasion in the ZHX3 knockdown bladder cancer cells." (PMID 37627900, 2023). "In bladder cancer tissues, ZHX3 expression negatively correlated with RGS2 expression." (PMID 37627900, 2023). "Bladder cancer patients with high ZHX3 and low RGS2 expression had the worst prognosis." (PMID 37627900, 2023). "Moreover, RhoA activity was decreased in ZHX3-knockdown bladder cancer cells but was significantly increased in ZHX3-knockdown bladder cancer cells treated with siRGS2." (PMID 37627900, 2023). "Thus, ZHX3 is an independent prognostic factor of bladder cancer." (PMID 37627900, 2023). "Thus, ZHX3 could be used as a prognostic biomarker for bladder cancer." (PMID 37627900, 2023).
clear cell renal carcinoma (2 papers, 2020 to 2022). A malignant epithelial neoplasm of the kidney characterized by the presence of lipid-containing clear cells within a vascular network. "Studies showed that ZHX3 was upregulated and might be an independent indicator of the OS in renal clear cell carcinoma." (PMID 31856408, 2020). "A study on clear cell renal cancers (ccRCC) based on an online database showed that both ZHX1 and ZHX3 expression levels were downregulated, while ZHX2 was upregulated." (PMID 36232466, 2022).
lymph node metastases (2 papers, 2022 to 2025). "As seen with ZHX1, ZHX3 showed a lower expression in cancers, and was associated with a high-risk of lymph node metastasis and worse outcomes." (PMID 36232466, 2022). "Interestingly, a lower ZHX3 expression in the tumor had a significantly greater risk of lymph node metastasis and was associated with a poorer survival time." (PMID 36232466, 2022). "Increased ZHX3 expression indicated a better OS in patients with and without lymph node metastases (N0, N1, and N2)." (PMID 41480542, 2025). "High ZHX3 expression also represented longer OS times in patients without lymph node metastases (N0) and in patients without distant metastasis (M0)." (PMID 41480542, 2025).
COVID-19 (1 paper, 2023). A disease caused by infection with severe acute respiratory syndrome coronavirus 2. "Migration of ZHX3, an ANGPTL4 repressor, from the slit diaphragm into the podocyte nucleus by COVID-19 cocktails parallels similar observations in human and experimental FSGS." (PMID 37040185, 2023).
hepatocellular carcinoma (1 paper, 2022). A malignant tumor that arises from hepatocytes. "ZHX3 is a transcriptional repressor, and in particular a failure of ZHX3 expression may be a cause of hepatocellular carcinoma." (PMID 36580499, 2022).
lung carcinoma (1 paper, 2025). "Increased ZHX3 mRNA expression was shown to be associated with a prolonged OS rate in patients with lung cancer." (PMID 41480542, 2025). "Regarding lung cancer, however, only three analyses reported lower ZHX3 expression." (PMID 41480542, 2025). "Additionally, analysis from the CCLE database demonstrated that the mRNA levels of ZHX1, ZHX2 and ZHX3 in lung cancer cell listed in the 19th, 25th, and 10th highest positions across all types of cancer, respectively." (PMID 41480542, 2025). "Relationship between ZHX3 expression and clinicopathological characteristics in lung cancer." (PMID 41480542, 2025). "Our results suggest that dysregulation of ZHX factors is involved in disease progression of lung cancer and ZHX3 expression may serve as a novel and promising biomarker for survival prediction in LUAD patients." (PMID 41480542, 2025).
renal carcinoma (1 paper, 2022). A carcinoma arising from the epithelium of the renal parenchyma or the renal pelvis. "A recent study on renal carcinoma showed a tumor-suppressive role for ZHX3." (PMID 36232466, 2022).
cancer (8 papers, 2017 to 2025). A tumor composed of atypical neoplastic, often pleomorphic cells that invade other tissues. "Changes and failure to express KMT2D and ZHX3 respectively are associated with cancer development, and a significant increase in cell growth after suppressing both is consistent with these functions." (PMID 36580499, 2022). "We further investigated ZHX3 mRNA expression among various types of cancer using the TIMER online database." (PMID 41480542, 2025). "Of note is that high ZHX3 protein expression was also found in 56.1% (46/82) of adjacent non-cancerous tissues, which was significantly higher than that in cancer tissues." (PMID 41480542, 2025). "It has been suggested ZHX family members act as tumor suppressors, although the functions of ZHX3 are still undefined in cancer." (PMID 28152006, 2017). "In addition, the expression of ZHX3 was found to be inversely related with the expressions of NMI and ARPC5, which have been associated with proliferation and motility of cancer cells, respectively." (PMID 28152006, 2017). "Zinc Finger E‐box Binding Homeobox 1 (ZEB1) and zinc fingers and homeoboxes 3 (ZHX3) have been extensively implicated in promoting epithelial‐mesenchymal transition (EMT), enhancing tumor cell migration and invasion, and thereby contributing to cancer aggressiveness and poor prognosis." (PMID 41020579, 2025). "Third, previous studies of LRRC17, ZHX3, LYPD6B, KIAA2022, and CMBL in cancer still remain paucity despite the importance of them." (PMID 31856408, 2020). "Moreover, while ZEB1 was identified as a direct downstream target of miR‐143‐3p, the regulatory relationships involving ZHX3 and ZNF148 in ESCC remain to be elucidated given their structural similarity and potential roles in cancer progression." (PMID 41020579, 2025). "Although it is now well established that ZHX1 and ZHX2 worked as tumor suppressors, the role of ZHX3 in cancer is not clear." (PMID 31856408, 2020). "In the present study, the expressions of ZHX1 and ZHX3 were reduced in ccRCC, but the expression of ZHX2 was increased in ccRCC compared to the normal tissues, which suggests the expressions of ZHX family members are cancer type-specific." (PMID 28152006, 2017).
tumor (6 papers, 2017 to 2025). "Further, we characterized ZHX3 protein expression profile to confirm its prognostic impacts using a cohort of 96 tumor samples by immunohistochemistry." (PMID 41480542, 2025). "A high level of ZHX3 protein expression was observed in the cytoplasm of tumor cells in 31.3% (30/96) of the LUAD samples tested." (PMID 41480542, 2025). "ZHX3 expression was also remarkably decreased in non-small cell lung cancer (NSCLC) in comparison to the adjacent non-tumor tissues." (PMID 36232466, 2022). "The expressions of ZHX1 and ZHX3 in most ccRCC tissues were lower than in paired non-tumor tissues, whereas ZHX2 expression was higher in most ccRCC tissues." (PMID 28152006, 2017). "ZHX3 was first identified as a suppressor of the AFP gene in HCC and was a good candidate for the tumor suppressor present at 16q22." (PMID 36232466, 2022).
hematological malignancies (1 paper, 2020). "Among the identified seven genes (LRRC17, ZHX3, CD38, AKR1B10, LYPD6B, KIAA2022, and CMBL) in our study, CD38 was well known about its correlation with hematological malignancies." (PMID 31856408, 2020).
ZHX3 also shares sentences with these, for which no sentence is quoted: liver cancer (2 papers); bladder urothelial carcinoma (1); depression (1); hypertriglyceridemia (1); lung adenocarcinoma (1); non-small cell lung carcinoma (1); ovarian carcinoma (1); renal cell carcinoma (1).